TAF5L (TATA-box binding protein associated factor 5 like)
Description:
Functions as a component of the PCAF complex. The PCAF complex is capable of efficiently acetylating histones in a nucleosomal context. The PCAF complex could be considered as the human version of the yeast SAGA complex (Probable). With TAF6L, acts as an epigenetic regulator essential for somatic reprogramming. Regulates target genes through H3K9ac deposition and MYC recruitment which trigger MYC regulatory network to orchestrate gene expression programs to control embryonic stem cell state (By similarity).
Synonyms: PAF65B
Tractability: PROTAC: ubiquitination databases record sites on it; its protein half-life has been measured.
Gene: Protein-coding gene on chromosome 1 (229,593,111 to 229,626,122, reverse strand). Ensembl gene ENSG00000135801.
Subcellular location: Nucleus
Subcellular location (Human Protein Atlas): Nuclear speckles; Cytoplasmic bodies
Pathways (Reactome):
Chromatin organization: HATs acetylate histones
Gene Ontology:
Molecular function: protein binding; transcription coactivator activity
Biological process: regulation of transcription by RNA polymerase II; positive regulation of DNA-templated transcription; regulation of DNA repair; regulation of DNA-templated transcription; regulation of RNA splicing; regulation of somatic stem cell population maintenance; transcription by RNA polymerase II
Cellular component: nuclear speck; nucleus; SAGA complex; transcription factor TFTC complex
Genetic constraint (gnomAD): Loss-of-function variants: 6 observed, 53.94 expected, observed/expected ratio (o/e) 0.11, 90% interval 0.06 to 0.22. The upper end of that interval is the gene's LOEUF score, 0.22, which puts it in group 1 of 6, group 1 being the genes least tolerant of losing a copy. Missense variants: 572 observed, 788.33 expected, observed/expected ratio (o/e) 0.73, 90% interval 0.68 to 0.78. Synonymous variants: 290 observed, 322.17 expected, observed/expected ratio (o/e) 0.9, 90% interval 0.82 to 0.99.
Homologues: Orthologues: chimpanzee TAF5L (100% identical), macaque TAF5L (99% identical), dog TAF5L (99% identical), rabbit TAF5L (99% identical), guinea pig TAF5L (95% identical), pig TAF5L (95% identical), rat Taf5l1 (94% identical), mouse Taf5l (93% identical), tropical clawed frog taf5l (81% identical), zebrafish taf5l (69% identical), Drosophila melanogaster wda (29% identical). Paralogues in human: TAF5 (40% identical).
Diseases named in the same sentence as TAF5L in open-access papers:
TAF5L is named in the same sentence as 10 diseases in open-access papers, as found by Europe PMC text mining. Sharing a sentence is not in itself a finding about the gene and the disease. The quoted sentences say what the papers report.
breast carcinoma (2 papers, 2013 to 2021). "In the present study, we investigated the clinical significance of the candidate biomarkers GGH FAAH, PIR and TAF5L in predicting breast cancer progression." (PMID 23374458, 2013). "According to a study, TAF5L was reported as a biomarker in breast cancer." (PMID 33991433, 2021). "In the present study, the nuclear expression of TAF5L was significantly down-regulated in invasive breast tumor tissues compared to the non-cancerous tissues, which suggests a potential tumor suppressor role in breast cancer." (PMID 23374458, 2013). "The TAF5L was pronouncedly down-regulated in primary invasive breast cancer tissues compared to matched adjacent non-cancerous tissues." (PMID 23374458, 2013).
myeloma (1 paper, 2024). "Among the proteins not previously linked to MM were three members (TAF5L, SUPT7L and SUPT20H) of the SAGA complex, a posttranslational regulator of MYC transcriptional activity that is important for myeloma growth." (PMID 38942927, 2024).
neuroblastoma (1 paper, 2024). Neuroblastoma (NB) is the most common solid, extracranial childhood tumor. "Among the most enriched differential gene dependencies observed in MYCN-amplified neuroblastoma as compared to all other solid tumor lineages were TADA2B, TADA1, SUPT20H, and TAF5L, along with several other members of the core and KAT modules." (PMID 38820154, 2024).
type 1 diabetes (1 paper, 2007). "We found some evidence of associations between type 1 diabetes and TAF5L, PDCD1, TCF7 and IL6 (ORs = 1.05 – 1.13; P = 0.0291 – 4.16 × 10-4)." (PMID 18045485, 2007). "Consequently, additional studies will be required to ascertain the contribution of TAF5L, PDCD1, TCF7 and IL6 to type 1 diabetes susceptibility." (PMID 18045485, 2007). "TAF5L, PDCD1, TCF7, IL6 and ICAM1 may be amongst the numerous loci with small effects in type 1 diabetes." (PMID 18045485, 2007).
tumor (2 papers, 2013 to 2021). "The discordant results detected between mRNA and protein expression of FAAH, PIR and TAF5L, could be due to multiple factors including, tumor heterogeneity, posttranscriptional regulation, differences in mRNA and protein turnover rates or poor specificity of the antibody used for IHC." (PMID 23374458, 2013). "A significant lower expression of TAF5L was observed in tumor cells compared with their adjacent non-cancerous cells." (PMID 23374458, 2013).
infection (1 paper, 2024). The state of being infected such as from the introduction of a foreign agent such as serum, vaccine, antigenic substance or organism. "We next examined virus-specific regulators, identifying knockout of TAF5L as increasing EBOV and SUDV infection levels while decreasing infection levels of the more distantly related MARV." (PMID 38617272, 2024).
TAF5L also shares sentences with these, for which no sentence is quoted: anemia (1 paper); breast tumor (1); cancer (1); invasive breast carcinoma (1).